IL13 (interleukin 13)
Diseases named in the same sentence as IL13 in open-access papers (continued):
Sharing a sentence is not in itself a finding about the gene and the disease.
asthma (continued). "Increased IL-4 and IL-13 levels over healthy controls are a hallmark of T2-high asthma and are important in eCOPD as well." (PMID 39766355, 2024). "In asthma model mice, deficiency of both IL-4 and IL-13 markedly reduced the number of eosinophils in airway, and induced blood eosinophilia." (PMID 38745653, 2024). "In type 2-high asthma, type 2 inflammation is present with its associated cytokines IL-4, IL-5, and IL-13, high levels of blood and/or sputum eosinophils, and elevated FeNO." (PMID 39765793, 2024). "Asthma was associated with the increased expression of pro-inflammatory cytokines, including IL-2, IL-5, IL-13, IL-17A, IL-22, IL-33, and TNF-α, and reduced levels of anti-inflammatory cytokine, IL-10 and adipokine, leptin in the circulation." (PMID 39902293, 2024). "IFN-γ, a key driver of airway neutrophil recruitment and overall lung inflammation along with IL4 and IL13, pivotal Type 2 cytokines, underscored the complex regulatory network underlying allergic inflammation in asthma." (PMID 38317239, 2024). "IL-13, being an important mediator for T-helper type 2 inflammation, is a cytokine linked to conditions such as asthma and AD." (PMID 39064040, 2024). "For instance, eosinophilic airway inflammation associated with TH2 cytokines (IL-4, IL-5, and IL-13) and/or Ig E is an underlying pathological mechanism in both chronic rhinosinusitis with nasal polyps and asthma." (PMID 38919942, 2024). "The equilibrium between mucin secretion and its removal is delicate; disturbances in this balance, often caused by cytokines like IL-4 and IL-13, are associated with diseases such as asthma, AR, and CRS." (PMID 38680486, 2024). "The genes associated with signalling of IL‐4 and IL‐13 pathways were downregulated in COPD eosinophils compared to asthma." (PMID 39422548, 2024). "The pathogenesis of asthma has been linked to an imbalance between Th2 and Th1 cells, resulting in increased levels of interleukin (IL)-4, IL-5, and IL-13 and decreased levels of interferon (IFN)-γ." (PMID 39539452, 2024). "CircARRDC3 can promote mucus generation and aggravate inflammation of IL‐13‐treated nasal epithelial cells during allergic rhinitis, serving as the prominent risk factor related to asthma progression." (PMID 39239069, 2024). "Th2-driven (IL-4/IL-13) airway diseases, such as asthma, cause goblet cell metaplasia, accompanied by increased mucus production and airway secretions." (PMID 39255033, 2024). "There is increasing evidence that asthma is associated with persistent low-grade inflammation, indicated by higher levels of inflammatory markers such as IL-4, IL-5, and IL-13." (PMID 39372270, 2024). "This disease has mainly been associated with Th2 cell cytokines, i.e., IL-4, IL-5, and IL-13, however recent developments have led to a terminology of Th2-high and Th2-low asthma." (PMID 39239645, 2024). "Both activated Th2 cells and ILC2s produce large amounts of the type-2 cytokines IL-4, IL-5, IL-9, and IL-13, which in turn trigger hallmark asthma symptoms." (PMID 37612281, 2023). "IL-13 is a proinflammatory cytokine associated with several inflammatory conditions, such as asthma, atopic dermatitis, and IBD." (PMID 36749569, 2023). "This study showed that Cd4-Cre::Acc1fl/fl mice exhibited attenuated AHR and airway inflammation in OVA- and HDM-induced asthma models due to the enhanced apoptosis and loss of Gata3, Il4, and Il13 expression in lung iNKT cells." (PMID 37917548, 2023). "IL-13 is a mucosal-associated cytokine that is known to influence asthma and is suggested to contribute to Line19F disease in mice." (PMID 37243153, 2023). "The TT genotype and allele T of IL13 rs1800925 are associated with severe and uncontrolled asthma (p < 0.05)." (PMID 37465198, 2023). "Although IL-5+ and IL-13+ Tc cell levels were increased in all patient groups compared to HCs, IL-9+ Tc cell frequencies were specifically associated with uncontrolled asthma." (PMID 37612281, 2023).
asthma (continued). "IL-5 and IL-4/IL-13 are considered the key drivers of type 2 pathways underlying eosinophilic airway inflammation in asthma." (PMID 37108417, 2023). "Upregulated M2 macrophages overexpress monocyte chemotactic protein-1 (MCP-1), IL-8, IL-13, etc., which can increase the risk of inflammation and asthma onset." (PMID 37569643, 2023). "It wasalso determined that the CC genotypes of IL4 rs2243250, IL6rs1800795, IL13 rs1800925 and the allelic variant T of IL12Brs3212220 can be considered to be potentially protective forthe development of uncontrolled asthma." (PMID 37465198, 2023). "Both IL-5 and IL-13 have important roles in lung inflammation associated with asthma, COPD, and chronic rhinitis." (PMID 37107767, 2023). "Functionally, Th2A cells have increased expression of IL-5 and IL-9 but a similar expression of IL-4 and IL-13 compared with conventional Th2 cells, aligning with the asthma-associated cluster identified transcriptionally." (PMID 37163370, 2023). "The IL4 and IL13 genes are located in one cluster of chromosome5q31.1 and encode cytokines that play a key role inthe asthma pathogenesis, namely, IL-4 and IL-13 promoteairway eosinophilia, mucus hyperproduction, bronchial hyperreactivity,and IgE synthesis." (PMID 37465198, 2023). "The metabolism of arachidonic acid can produce cysteinyl leukotrienes, which is overexpressed in asthma patients and has recently been linked to the production of IL-4, IL-5, and IL-13 by binding ILC2 and Th2 cells." (PMID 37680636, 2023). "In patients with asthma, levels of type-2 instructional cytokines (IL-33 and IL-25) and effector cytokines (IL-4, IL-5, and IL-13) are elevated in the airway mucosa, associated with impaired antiviral immunity." (PMID 37174726, 2023). "The proportion of ADRB2 rs1042713 A allele, IL4 rs2243250 T allele, FCER1B rs569108 A allele, and IL13 rs20541 G allele in the asthma group was higher than those in the control group." (PMID 38049812, 2023). "both the CT genotype of IL4 rs2243250 and the T alleleof IL13 rs1800925 were associated with both controlled anduncontrolled asthma, with the TT genotype of IL13 rs1800925being associated with with uncontrolled one." (PMID 37465198, 2023). "Reduced expression of the barrier forming claudins -1, -3, -4 and -18 is associated with increased IL-13 production in asthma, from mild-moderate to severe asthma." (PMID 37520564, 2023). "Liu Z., Li P., Wang J., Fan Q., Yan P., Zhang X., Han B. A meta-analysisof IL-13 polymorphisms and pediatric asthma risk." (PMID 37465198, 2023). "Alongside the canonical cytokines IL-4, IL-5, and IL-13, it is also clear that human Th2 cells can take on characteristics normally associated with other Th subsets in asthma." (PMID 37163370, 2023). "IL-13 is a Th2 cytokine produced by Th2-polarized cells that is associated with allergic diseases, asthma, and tissue fibrosis." (PMID 36743413, 2023). "Interleukin-13 (IL-13), is a pleiotropic cytokine that is known to be associated with airway inflammation in asthma and reactive airway diseases, in neoplastic and autoimmune diseases." (PMID 37041520, 2023). "Pb exposure downregulates interleukin-13 expression and can increase the risk of asthma-related immunomodulatory abnormalities in preschool children." (PMID 36969623, 2023). "Asthma associated pink and purple modules in AECs and blue and brown modules in NECs, and associated pathways showed an overlapped asthma related pathways including IL-13 Signaling and PI3K/AKT Signaling and apoptosis signaling." (PMID 37438356, 2023). "Even the expression of IL-13, an interleukin produced by Th2 cells and responsible for the inflammation and symptoms associated with severe asthma, would seem to be favored by miR-21." (PMID 37892224, 2023). "RNAseq analysis further demonstrated enrichment of contractile and remodeling-relevant pathways in TGF-β1 and IL-13 treated tissues as well as pathways generally associated with asthma." (PMID 37206658, 2023).
asthma (continued). "In a study evaluating the plasma of patients with asthma, IL-10 and IL-13 were elevated, associating both with an important role in inflammation." (PMID 37834157, 2023). "Omraninava M., Eslami M.M., Aslani S., Razi B., Imani D., Feyzinia S.Interleukin 13 gene polymorphism and susceptibility to asthma: ameta-regression and meta-analysis." (PMID 37465198, 2023). "Type 2-high asthma is based on the presence of cytokines associated with type 2 inflammation (IL-4, IL-5, and IL-13), high levels of blood and sputum eosinophils, and elevated Fraction of exhaled Nitric Oxide." (PMID 38062491, 2023). "Proinflammatory cytokines IL-4 and IL-13 secreted by Th2 are closely associated with mucus secretion, eosinophil activation, and airway remodeling in asthma." (PMID 37873538, 2023). "Allelefrequency analysis revealed the differences in the frequency ofthe rare T allele of IL13 rs1800925 between groups of childrenwith both controlled and uncontrolled asthma, and healthychildren as well ( p < 0.05)." (PMID 37465198, 2023). "IL-13 has been implicated in the pathogenesis of various inflammatory and allergic diseases, including asthma, allergic rhinitis, and atopic dermatitis." (PMID 37568438, 2023). "Asthma-associated biomarkers include immune cells (T-helper, Th1, Th2), cytokines (IL-4, IL-13), eosinophils, mast cells, and neutrophils that form an inflammatory infiltrate in the lung airways causing adverse symptoms." (PMID 36115955, 2022). "The suppressed expression of MMP-9 by DADS treatment caused a reduction in IL-4, IL-5, IL-13, and IgE in the lung tissue of rats with asthma." (PMID 36555240, 2022). "The proinflammatory cytokines, TNFα and IL-13, which are heavily implicated in asthma severity, were shown to decrease SERCA2 expressions in human airway smooth muscle cells." (PMID 36685580, 2022). "Genetic investigations have also detected relevant linkages of IL-13/IL-13 receptor gene polymorphisms with airway hyperresponsiveness and asthma prevalence." (PMID 35350765, 2022). "In HBE cells, TNC expression is increased by rhinovirus infection, a risk factor for asthma, and type 2 cytokines including IL-4 and IL-13, critical mediators of asthma development." (PMID 35053372, 2022). "Beyond B and T lymphocytes, within the airways IL-4 and IL-13 target other immune/inflammatory and resident cells implicated in asthma pathobiology." (PMID 35746582, 2022). "In particular, by blocking at the receptor level the pathogenic actions of both IL-4 and IL-13 within the context of type 2 inflammation, dupilumab behaves as a very effective biologic drug for the treatment of severe asthma." (PMID 35746582, 2022). "Asthma has long been considered as a Th2-associated inflammatory disease, with IL-4, IL-5, and IL-13 as the key cytokines and eosinophilic infiltrates in the airways." (PMID 35408882, 2022). "IL13 has also been reported to be associated with mitochondrial dysfunction in an animal-induced asthma model." (PMID 36497047, 2022). "The polymorphisms found in the RAD50-IL-13 region of chromosome 5q31.1 of IL-13 is involved in determining the individual predisposition to asthma." (PMID 36483465, 2022). "It has been well documented that type 2 cytokines IL-5 and IL-13 are implicated in the pathogenesis of the eosinophil-rich airway inflammation, which typically characterizes asthma." (PMID 35524325, 2022). "Asthma and allergies in the airways are usually associated with increased mucus production due to the activity of mast cells’ IL-1β and IL-13." (PMID 35266441, 2022). "Remarkably, although Th17 responses have been reported to counter-regulate Th2 responses and vice versa, under certain conditions IL-13 and IL-17A appear to act synergistically on the inflammatory response underlying asthma formation." (PMID 35883573, 2022). "This discovery was followed by more biological agents targeting key inflammatory nodes in the chronic inflammation underlying asthma, such as IL-5, IL-5R, IL-13 and IL-4R." (PMID 36561741, 2022).
asthma (continued). "According to reports, genetic polymorphisms affecting the IL-4/IL-13 axis were associated with asthma susceptibility and risk association between IL-4 and IL-13 genes polymorphisms and food allergy." (PMID 36364962, 2022). "It is well known that IL-13 causes an over-reaction in the airways and IL-4 stimulates mucus secretion, which are obvious indicators of asthma." (PMID 35419072, 2022). "It was also found that the AA genotype of the IL-13 R130Q (rs20541) locus polymorphism was significantly more common in children with asthma than in healthy subjects." (PMID 35629280, 2022). "Next, Elevated serum total IgE levels, as marker for asthma, was obviously decreased in sTSLP group, as well as levels of Th2-associated cytokines (IL-4, IL-5 and IL-13) in the BALF of mice." (PMID 35351157, 2022). "Children with a specific polymorphism of IL-13 and in utero exposure to smoke were at higher risk of wheezing at age four and persisting asthma at age ten years." (PMID 36362786, 2022). "The alternative activation of macrophages is induced by different cytokines, one of these is IL-13, which is produced by T lymphocytes, granulocytes and macrophages, and is associated with asthma development and lung tissue fibrosis." (PMID 36648870, 2022). "Exuberant production of IL‐4, IL‐5, and IL‐13 leads to asthma features with the accumulation of type 2‐associated cells, such as eosinophils, in lung tissue." (PMID 35758054, 2022). "Some IL13 polymorphisms increase the expression of IL13 messenger ribonucleic acid and protein in the blood, bronchial washes, and sputum of patients with asthma or COPD." (PMID 36497047, 2022). "Interleukin (IL)-4 and IL-13 are critical cytokines in the induction of the pathogenic Th2 responses in AR and asthma." (PMID 35663523, 2022). "The maternal cytokine profile during the third trimester of pregnancy (defined as the ratio of IFN‐γ and IL‐13 secreted by mitogen‐stimulated maternal peripheral blood mononuclear cells) has an inverse association with childhood asthma risk." (PMID 36073598, 2022). "Allergen exposure causes an increase in airway remodelling markers in patients with asthma, with IL-13 an underlying driver of the process." (PMID 36289834, 2022). "Despite some similarities between the bioactivities of IL-4 and IL-13, however, each of these cytokines also plays distinct pathogenic roles in asthma." (PMID 35746582, 2022). "CD4+CRTH2+CCR6+ cells secrete IL-17, IL-4 and IL-13, leading to the infiltration neutrophils and eosinophils, which is responsible for chronic inflammation associated with asthma." (PMID 34090369, 2021). "IL-4 and IL-13 are essential for the induction and persistence of the type 2 immune response, and they are associated with multiple atopic diseases, such as asthma and atopic dermatitis." (PMID 33450900, 2021). "The elite group of susceptible genes of asthma and atopy replicated in more than ten different studies include IL13, IL4, IL4RA, FCER1B and ADRB2, five important inflammatory genes associated with IgE levels." (PMID 34243801, 2021). "IL13 is thought to play a central role in promoting mucus production associated with asthma and COPD, making IL13 neutralizing biologics the focus of both an approved therapeutic, dupilumab, and multiple other ongoing clinical trials." (PMID 34305924, 2021). "Mechanistically, EM900 was found to significantly decrease the expression of asthma-associated inflammatory mediators such as IL-5, IL-13, CCL5 and CXCL2 by lung interstitial macrophages, via the suppression of NF-κB and p38 signaling." (PMID 34456917, 2021). "IL-13 is a key pathogenic player in asthma that is known to induce mononuclear and eosinophilic inflammation, mucus hyperplasia with cellular metaplasia, and fibrosis in the subepithelial layers of the airways, eventually ending up with airway obstruction." (PMID 33688506, 2021).
asthma (continued). "Since CP and OA inhibited IL-5 in BALF and Th2 cytokine (IL-5, IL-4, and IL-13) production in spleen cells, we assessed the mRNA expression of asthma-associated cytokines and mediators in the lung tissues of OVA-induced asthmatic mice using qRT-PCR." (PMID 33806085, 2021). "In asthma pathogenesis, the overexpression of several type 2 inflammatory mediators including IgE, IL-4, IL-5, IL-13, and TSLP has been associated with ASM hyperreactivity, all of which can be targeted by humanized monoclonal antibodies (mAbs)." (PMID 34572466, 2021). "The pathogenic mechanisms of AD are similar to asthma, as they are both Th2-driven diseases with the enhancement of IL-4, IL-5, and IL-13 cytokines that can induce eosinophils and IgE recruitment." (PMID 34572281, 2021). "Increased level of Th2 cytokines such as IL-13 has been frequently associated with mucus secretion and is consequently believed to be a major contributor of goblet cell hyperplasia during asthma." (PMID 35386975, 2021). "While only preliminary studies, these trials further solidify that IL-4- and IL-13-related inflammation are directly linked to asthma, and can be a target for therapeutic intervention." (PMID 34948449, 2021). "Eosinophilic inflammation is a hallmark of all forms of asthma, and is a consequence of the uncontrolled production of IL-4, IL-13, and IL-5." (PMID 34948449, 2021). "These lung-specific effects of IL-13 are also consistent with other work showing that pulmonary eosinophilia is impaired in IL-13Rα1–deficient mice during asthma." (PMID 34127548, 2021). "Type 2 (T2)-high asthma is associated with elevated levels of Th2 cytokines such as IL-4, IL-5 and IL-13 whereas T2-low asthma is mainly linked to the activation of Th1 and Th17 cells." (PMID 34777398, 2021). "ILC2s are important sources of Th2 cytokines such as IL-5 and IL-13 that contribute to the increased Th2-associated airway inflammation observed in asthma." (PMID 34101619, 2021). "Murine asthma models have also shown that elevated IL-13 and dampened IFN-γ levels are associated with elevated viral loads and lung tissue destruction following pH1N1 infection." (PMID 33653328, 2021). "Asthma is thought to be a Th2 cell-associated inflammatory disease, and Th2-type cytokines, such as IL-4 and IL-13, which can activate B cells to produce allergen-specific IgE, are considered to drive disease pathology in patients." (PMID 34421593, 2021). "Autophagy is somehow linked to asthma pathogenesis—increased autophagy was noted in bronchial tissue from asthmatic patients, autophagy is also important for IL-13-dependent up-regulation of mucus production." (PMID 33661375, 2021). "Our previous study showed the association of IL-4, its receptor IL4Rα and IL-13 polymorphisms with asthma in the same pediatric cohort that was analyzed in this study." (PMID 34946286, 2021). "Asthma is caused by hyperreactivity to benign antigens, with humoral immunity orchestrated by interleukin-4 (IL-4) and IL-13 being the key etiological factor." (PMID 33976140, 2021). "Several pathophysiological pathways are associated with the development of asthma, including those that mediate the release of cytokines involved in the inflammatory process, in particular IL-4, IL-9, IL-13, and IL-17." (PMID 33577738, 2021). "Despite the glucocorticoid therapies have a great effect on maintaining the balance of Th1/Th2 in asthma, more studies have paid attention to various treatments targeting Th2-associated IL-4, IL-5, or IL-13." (PMID 33013382, 2020). "A recent study confirmed that interleukin-13 (IL-13)+ type 2 innate lymphoid cells (ILC2s) in peripheral blood are associated more strongly than Th2 cells with asthma severity and GC resistance in humans." (PMID 32112175, 2020). "Elevated bronchial expression of IL-5 and IL-13 has been shown to be associated with sputum and blood eosinophilia and moderate-to-severe asthma." (PMID 33322143, 2020).